KLF7 (KLF transcription factor 7)
Diseases named in the same sentence as KLF7 in open-access papers (continued):
Sharing a sentence is not in itself a finding about the gene and the disease.
Hearing impairment (1 paper, 2021). A decreased magnitude of the sensory perception of sound. "These two processes have important influences on the auditory system, and therefore disruption of KLF7 could lead to hearing impairment and dysfunction." (PMID 33805165, 2021).
hearing loss (1 paper, 2021). "As KLF7 gene was reported to be expressed in the inner ear and associated with human hearing difficulties, our findings could provide clues for further elucidating novel genetic causes for human hearing loss." (PMID 33805165, 2021).
infarct (1 paper, 2021). "In accordance with our infarct core-to-border axis (punch positions 5–8) analysis, we found that seven of the KLF family of TFs (KLF2–4, 6–8, and 12) were significantly depleted in glutamatergic neurons at the glial scar in the stroke hemisphere (KLF4 and KLF7 shown)." (PMID 33627658, 2021).
Intellectual disability (1 paper, 2022). "Studies have shown that individuals with klf7 mutations are associated with intellectual disability." (PMID 35328799, 2022).
liver cancer (1 paper, 2023). An epithelial or non-epithelial malignant neoplasm that arises from the liver. "To investigate the molecular mechanism underlying KLF7-mediated HCC metastasis, we compared transcriptome changes between PLC/PRF/5-control and PLC/PRF/5-KLF7 cells using a Human Liver cancer RT2 Profiler PCR Array." (PMID 37554278, 2023). "Correspondingly, by employing gene signature analysis in online LIHC databases, we found that the mean expression of the gene set composed of KLF7, TLR4 and PTK2 was elevated in liver cancer tissues compared to normal livers, and further increased in liver cancer metastatic tissues." (PMID 37554278, 2023).
osteoporosis (1 paper, 2022). A condition of reduced bone mass, with decreased cortical thickness and a decrease in the number and size of the trabeculae of cancellous bone (but normal chemical composition), resulting in increased fracture incidence. "Molecular and cell experiments were performed to prove that KLF7 accelerates osteoclast differentiation by suppressing HO-1, thereby the development of osteoporosis was affected." (PMID 35419025, 2022). "The result of this study disclosed the molecular mechanism of KLF7/HO-1 in osteoporosis, which provides theoretical basis for clinical treatment and drug development of osteoporosis." (PMID 35419025, 2022). "Therefore, we plan to carry out further animal experiments to further explore the therapeutic value of KLF7 in osteoporosis." (PMID 35419025, 2022). "The results of this study confirmed that the TF KLF7 could induce osteoclast differentiation by inhibiting HO-1, thereby promoting the development of osteoporosis." (PMID 35419025, 2022). "Recently, a bioinformatics study suggested that KLF7 can affect patient’s BMD, which makes it a key target of osteoporosis." (PMID 35419025, 2022). "Due to the limitations of bioinformatic studies, the biological role of KLF7 in osteoporosis has not been fully elucidated yet." (PMID 35419025, 2022).
pancreatic ductal adenocarcinoma (1 paper, 2021). An infiltrating adenocarcinoma that arises from the epithelial cells of the pancreas.
pinguecula (1 paper, 2021). A yellowish thickened lesion on the conjunctiva near the cornea representing a benign degenerative change in the conjunctiva caused by the leakage and deposition of certain blood proteins through the permeable capillaries near the limbus. "KLF5 and KLF7 encode transcription factors that oppose KLF4 activity; their expression did not change in pterygium or pinguecula." (PMID 34769520, 2021).
pterygium (1 paper, 2021). A wedge-shaped fibrovascular lesion arising from the bulbar conjunctiva and extending to the cornea. "An increase in EMT in corneal epithelium in pterygium is also suggested, regulated by KLF7, BMP2, BMP6, and SNAI1." (PMID 34769520, 2021). "Our further analysis of pathways controlled by upstream regulator TP63 suggested increased EMT in pterygium, regulated by BMP2, BMP6, SNAI1 and KLF7." (PMID 34769520, 2021).
Sepsis (1 paper, 2022). Sepsis is defined as life-threatening organ dysfunction caused by a dysregulated host response to infection. "It has been recently demonstrated that the miR-19b-3p protects cells from sepsis-induced inflammation injury via inhibiting the NF-κB signaling pathway, and Krüppel-like factor 7 (KLF7) was a potential target." (PMID 35054993, 2022).
small cell lung carcinoma (1 paper, 2021). Small cell lung cancer (SCLC) is a highly aggressive malignant neoplasm, accounting for 10-15% of lung cancer cases, characterized byrapid growth, and early metastasis. "Finally, we show that SMAD3, ZNF217, KLF13, GATA2, GATA3, KLF7, and PHOX2B are components of CRCs in other cancers, including DLBCL, pancreatic, gastric, breast, and small cell lung cancer." (PMID 35201514, 2021).
spinal muscular atrophy (1 paper, 2019). A motor neuron disease that affect the muscles, and characterized by muscle weakness and atrophy resulting from progressive degeneration and irreversible loss of the anterior horn cells in the spinal cord (i.e., lower motor neurons) and the brain stem nuclei. "Furthermore, a dominant mutation in FBXO38 that renders it unable to bind KLF7 causes spinal muscular atrophy (SMA), an inherited disorder characterized by progressive muscle weakness." (PMID 30804394, 2019).
tongue cancer (1 paper, 2021). A malignant neoplasm affecting the tongue. "For instance, the prognostic significance of KLF7 was studied in tongue cancer." (PMID 35047407, 2021).
triple-negative breast carcinoma (1 paper, 2022). An invasive breast carcinoma which is negative for expression of estrogen receptor (ER), progesterone receptor (PR), and human epidermal growth factor receptor 2 (HER2). "Higher-graded tumors and more aggressive intrinsic tumor types, namely triple-negative breast cancer, showed high expression levels of KLF7." (PMID 36192788, 2022).
tumor (37 papers, 2015 to 2026). "Analysis of 24 distinct immune cell types revealed potential associations between KLF7 expression and the infiltration of specific immune cells within the tumor microenvironment." (PMID 38116138, 2023). "Tumor size demonstrated a significant association with KLF7 levels (P < 0.001), with larger tumors displaying higher KLF7 expression." (PMID 38116138, 2023). "The first pathway is necessary for KLF7-mediated PDAC tumor growth and metastasis, and the latter causes Golgi complex fragmentation and results in reduced protein glycosylation, leading to reduced secretion of chemokines." (PMID 37239940, 2023). "Elevated KLF7 expression is associated with larger tumor size, poor differentiation, advanced T and N stages, and receipt of chemotherapy." (PMID 38116138, 2023). "The upregulation of KLF7 expression in tumor tissues suggests its potential as a diagnostic biomarker for early detection and risk stratification." (PMID 38116138, 2023). "In addition, KLF7 could effectively destroy the histological barrier that blocks tumor, and eventually cause tumor cells to detach from the primary site with complete structure to damage surrounding tissues." (PMID 32063748, 2020). "Compared to the control group, the KLF7 downregulation (shKLF7 + Vehicle) greatly decreased tumour growth, suggesting that silencing of KLF7 suppressed HCC tumorigenesis." (PMID 39648156, 2024). "In vivo, the mice exposed to double tryptophan diet had a larger tumour size and weight, whereas mice with KLF7 knockdown exhibited smaller tumours." (PMID 39648156, 2024). "The H&E staining results indicated a reduction in the density of cancer cells within the tumor in the KLF7 stable knockdown group." (PMID 38164176, 2024). "The results indicated that KLF7 protein expression in COAD tumors was higher than in adjacent non-tumor tissues." (PMID 38164176, 2024). "KLF7 was significantly reduced in the tumours of shKLF7‐1 + Vehicle and shKLF7‐1 + DT as compared with other tumours." (PMID 39648156, 2024). "Conversely, KLF7 stable overexpression promoted tumor growth, significantly increasing tumor volume and weight." (PMID 38164176, 2024). "To answer this question, we detected HCC cell propagation and migration in vitro and tumour development in vivo under KLF7 knockdown and treatment with serotonin or its inhibitor." (PMID 39648156, 2024). "In HCC, our previous research showed the overexpression of KLF7 in HCC, and KLF7 drove tumour development and cell invasion of HCC by binding to the promoter of Ccdc85c." (PMID 39648156, 2024). "The results showed that KLF7 stable knockdown significantly decreased tumor volume compared to the control group." (PMID 38164176, 2024). "To gain deeper insights into the influence of KLF7 on tumor metastasis, we established an experimental metastasis model by intravenously injecting COAD cells into the tail vein of BALB/c nude mice." (PMID 38164176, 2024). "High KLF7 expression in LUAD was related to tumor size, lymph node metastasis, staging, low overall survival, and an independent prognostic factor." (PMID 38560274, 2024). "Regarding tumor differentiation grade, higher KLF7 expression was observed in poorly differentiated tumors compared to well-differentiated or moderately differentiated tumors (P = 0.032)." (PMID 38116138, 2023). "The protein and mRNA expression levels of KLF7 in the tumor tissues of PCa patients were also higher than those of BPH." (PMID 37170248, 2023). "Knockdown of KLF7 using shRNA resulted in a significant suppression of cell proliferation, indicating its involvement in promoting tumor growth." (PMID 38116138, 2023). "Functional assays demonstrated that silencing KLF7 resulted in reduced cell proliferation, migration, and invasion, indicating its involvement in promoting tumor growth and metastasis." (PMID 38116138, 2023). "In recent years, KLF7 has been found to play an important role in regulating inflammatory response and tumor progression." (PMID 37170248, 2023).
tumor (continued). "Compared with the normal diet group (ND), the expression levels of KLF7 in tumor tissues in high-fat diet group (HFD) were higher." (PMID 37170248, 2023). "HCC samples had higher KLF7 mRNA expression than adjacent non-tumor samples and normal livers, and HCC patients who had ever undergone recurrence or metastasis displayed elevated KLF7 expression compared to those without recurrence or metastasis." (PMID 37554278, 2023). "Immunohistochemical showed that the expression level of KLF7 protein in the tumor tissues of patients with PCa was significantly higher than that of BPH." (PMID 37170248, 2023). "Our results suggest that KLF7 acts as a tumor suppressor in GBC and it is partially regulated by miR-4733-5p." (PMID 35443866, 2022). "There is evidence that KLF7 and hypoxia work together to influence cell apoptosis, but it is not yet fully understood how they will act together to affect tumor development and progression." (PMID 35757722, 2022). "METTL3-catalyzed m6A modifications of the SET domain-containing 7 (SETD7) and kruppel-like factor 7 (KLF7) mRNAs, which function as tumor suppressors, are recognized by YTHDF2 for mRNA decay." (PMID 36226062, 2022). "Using “gain of function” and “loss of function” strategies in vitro and in vivo, we revealed that KLF7 promoted tumor growth and invasion in HCC cell lines." (PMID 33858520, 2021). "Comparing tumor to tumor in scenario 2, Ccl21 and Klf7 were normalized by SPI ingestion, relative to basal diet." (PMID 34494932, 2021). "For some genes, such as Klf7, both H3K4me1 and H3K27ac increased on the AP-1 enhancers in tumor tissues; for others, such as E2f8, H3K4me1 did not change obviously while H3K27ac significantly increased." (PMID 34409068, 2021). "Collectively, our data demonstrated that KLF7 promotes HCC tumor growth and invasion by stimulating the expression of VPS35." (PMID 33858520, 2021). "Our study confirmed that overexpression of VPS35, regulated by KLF7, promoted the tumor growth in vitro and in vivo, and contributed to cell invasion, cell cycle and blocked cell apoptosis." (PMID 33858520, 2021). "Correspondingly, the tumor size and weight were larger in mice injected with KLF7-overexpressing MHCC97H cells than tumors injected with empty vector cells (p < 0.001 for tumor weight)." (PMID 33858520, 2021). "In summary, our study demonstrated the crucial roles of KLF7/VPS35 axis in HCC tumor growth, cell invasion, cell cycle and cell apoptosis." (PMID 33858520, 2021). "Taken together, we reveal that GNA14/KLF7/HAS2 signaling cascade exerts tumor promoting function during UCEC development." (PMID 33892667, 2021). "The results of qRT-PCR showed that KLF7 expression was higher in GC tumor tissues than that in the corresponding paracancerous tissues." (PMID 32063748, 2020). "Functional in vitro studies demonstrated that KLF7 can play a role as oncogene, driving tumour growth and dissemination." (PMID 33250051, 2020). "In multivariate Cox regression analysis, after adjusting for age and residual tumor after primary surgery, KLF7 was identified as a powerful predictor of OS (p < 0.0001)." (PMID 33250051, 2020). "Among 24 down-regulated genes 15 (63%), 16 (67%) and 23 (96%) had consensus binding sites for c-Myc, Klf7 and Gata3, respectively while the entire composite module fitted 11 promoters or 46% of down-regulated tumor specific genes." (PMID 26427040, 2015). "Furthermore, western blot analysis of five paired tumor-normal human COAD samples revealed that KLF7 protein expression is upregulated in tumors relative to adjacent normal tissues." (PMID 38164176, 2024). "In conclusion, we suggest that KLF7 regulates the growth of HCC tumours through Trp metabolism." (PMID 39648156, 2024). "Additionally, in vivo experiments using xenografts derived from KLF7-knockout COAD cells showed a notable decrease in tumor growth rate compared to the control COAD cells." (PMID 38116138, 2023).
tumor (continued). "Furthermore, we explored the association between KLF7 expression and tumor TNM stages, revealing a positive correlation between higher levels of KLF7 and more advanced tumor stages." (PMID 38116138, 2023). "Moreover, the functional assays performed in vitro and in vivo provide mechanistic insights but do not fully elucidate the complex molecular pathways through which KLF7 influences tumor progression." (PMID 38116138, 2023). "KLF7—a ubiquitously expressed protein—is strongly expressed in tumor tissues." (PMID 36192788, 2022). "The mechanism of KLF7 promoting tumor may be related to KLF7 promoting the invasion of tumor cells into microvessels and promoting the formation of neovascularization." (PMID 35936369, 2022). "Given the fact that KLF7 was a direct target gene of miR-4733-5p and the oncogenic role of miR-4733-5p in GBC, we hypothesized that KLF7 might play a tumor suppressive role in GBC." (PMID 35443866, 2022). "Taken together, our data demonstrated high KLF7 expression levels in aggressive tumor types." (PMID 36192788, 2022). "Furthermore, it has been reported that KLF7 can enhance the ability of tumor migration and invasion, which is related to tumor recurrence and metastasis, whereas there are few studies on its expression in the serum of patients with NSCLC." (PMID 35936369, 2022). "By qualitatively and quantitatively influencing the cellular proteome, KLF7 expression in cancer cells might have far reaching implications for the tumor biology and the aggressiveness of the cancer." (PMID 36192788, 2022). "Xenografted tumor growth was used to assess in vivo role of KLF7." (PMID 33858520, 2021). "We hypothesized that KLF7 medicated its effects on HCC tumor growth and invasion by regulating target gene expression." (PMID 33858520, 2021). "Lastly, we explored whether KLF7/HAS2 cascade promoted xenograted tumor development by implanting equal number of Hec-1-B cells expressing Ctrl, KLF7 overexpressing, and KLF7 overexpressing plus shHAS2 lentiviruis onto female nude mice." (PMID 33892667, 2021). "Thus, in our study, we found that silence of KLF7 resulted in attenuated HCC tumor growth both in cultured cell and in mice study." (PMID 33858520, 2021). "We showed that KLF7 overexpressing accelerated xenograted tumor development of Hec-1-B cells, which could be reversed by HAS2 knockdown." (PMID 33892667, 2021). "KLF7 transcriptional activation of VPS35 was necessary for HCC tumor growth and metastasis." (PMID 33858520, 2021). "In addition, KLF7 enhanced VPS35 transcription that promoted HCC tumor growth and invasion by activating beta catenin signaling pathway." (PMID 33858520, 2021). "Consequently, the current study set out to elucidate the potential role of LINC00152 in PC, and our obtained findings indicated that silencing LINC00152 alleviated PC glycolysis and tumor growth via the miR-185-5p/KLF7 axis." (PMID 34659523, 2021). "We will also investigate the significance of KLF7 on tumor metastasis in vivo." (PMID 33858520, 2021). "Finally, overexpression of KLF7 partly blocked miR-136-3p-induced inhibition of tumor growth in vitro and in vivo." (PMID 32677950, 2020). "It showed that, in vivo tumor growth was significantly suppressed by miR-450b-3p upregulation, and overexpression of KLF7 could reverse the inhibitory effect of tumor growth in nude mice with miR-450b-3p mimic (p < 0.05)." (PMID 32063748, 2020). "Subsequently, we validated the reduction of weight in tumor-forming tissues of nude mice injected with miR-450b-3p mimic; as well as overexpression of KLF7 could reverse such effect (p < 0.05)." (PMID 32063748, 2020). "In addition, we subjected the tumour tissues to IHC staining of KLF7 and Ki‐67." (PMID 39648156, 2024). "Finally, we validated the effect of KLF7 on tumor growth in mice." (PMID 39097779, 2024). "We hypothesized that KLF7 plays a tumor-promoting role in this aggressive malignancy." (PMID 38116138, 2023).